ENSG00000200652
Synonyms: LOC124900376
Gene: Small nucleolar RNA gene on chromosome 16 (28,179,098 to 28,179,223, forward strand). Ensembl gene ENSG00000200652.
Gene Ontology:
Biological process: RNA processing
Cellular component: nucleolus
Homologues: Paralogues in human: SNORA25B (90% identical), SNORA25 (87% identical).